IL5 (interleukin 5)
Diseases named in the same sentence as IL5 in open-access papers (continued):
Sharing a sentence is not in itself a finding about the gene and the disease.
food allergy (39 papers, 2011 to 2025). Gastrointestinal disturbances, skin eruptions, or shock due to allergic reactions to allergens in food. "Comparatively, H2RA use is thought to increase risk of food allergy and anaphylaxis due to a pro-inflammatory effect that increases IgE and IL-5 levels." (PMID 40507633, 2025). "The key cytokines in food allergy—interleukin‐4 (IL‐4), IL‐5, and IL‐13—operate in peripheral tissues upon inflammatory stimuli." (PMID 40730516, 2025). "IL-5 promotes the accumulation of eosinophils in the gut in food allergies and exacerbates eosinophil-mediated inflammatory responses." (PMID 34684316, 2021). "Severe infiltration of CD4+ T cells and over production of the Th2 cytokines, including IL-4, IL-5 and IL-13 have been documented in the intestinal mucosa of humans and mouse models of GI food allergy." (PMID 31164117, 2019). "We identified two groups of SNPs covering IL5/RAD50 and IL4/KIF3A, which were significantly associated with food allergy." (PMID 29051540, 2017). "The Th2-related cytokines IL-4, IL-5, and IL-13 were increased in mLNs from food allergy-induced mice." (PMID 27445434, 2016). "These effector cells then release a collection of Th2 cytokines (IL-4, IL-5, IL-9, IL-13, IL-15 and IL-18) that are organized in the intestinal immune system for prompting food allergy or anaphylactic immune responses upon successive exposure to the antigen." (PMID 27840774, 2015). "These effector cells, through exposure to an array of Th2 cytokines (IL-4, IL-5, IL-9, IL-13, IL-15 and IL-18) in the intestinal immune system, are primed for food allergy or anaphylactic reactions upon subsequent antigen exposure." (PMID 27840774, 2015). "Furthermore, it has been found that chitosan oligosaccharides protect against shrimp protomyosin‐induced food allergy by downregulating IL‐4, IL‐5, and IL‐13 and upregulating interferon (IFN)‐γ." (PMID 40901656, 2025). "Interleukin 3 (IL-3), interleukin 5 (IL-5), and interleukin 13 (IL-13) were cytokines produced in a statistically significant way by peripheral blood mononuclear cells stimulated in vitro with cow’s milk in patients with food allergies." (PMID 37763228, 2023). "Since it has not been clearly defined which segment of the intestine is involved in food allergy-induced type 2 immune responses, we investigated the gene expressions of IL-4, IL-5, and IL-13 in the duodenum, jejunum, ileum, and colon by using quantitative PCR." (PMID 36501013, 2022). "CITRUS did not detect expression of the Th2 cell cytokines IL-5, IL-10, or IL-13, cytokines that are strongly associated with food allergy." (PMID 32698761, 2020). "Our finding showed lower values of IL-5 and this may be associated with our special category of non-IgE-mediated food allergy." (PMID 35458127, 2022). "As a result, we observed that dietary emulsifiers, especially P80, significantly exacerbated food allergy symptoms, with increased OVA-specific IgE induction and accelerated type 2 cytokine expressions, such as IL-4, IL-5, and IL-13, in the colon." (PMID 36501013, 2022). "Oral administration of DON together with whey protein facilitated food allergy induction, indicated by increased ASR values and serum levels of whey-specific IgE, and the production of IL-5 and IL-13 in re-stimulated splenocytes." (PMID 34975906, 2021). "Our data revealed that values of IL-4 and IL-13 are higher in infants with non-IgE-mediated food allergies, whereas IL-5 and IL-10 are lower, as observed in IgE-mediated food allergies." (PMID 35458127, 2022). "This is the first study that aims to detect the expression of Th2 cytokines (IL-4, IL-5, IL-10, and IL-13) in infants with non-IgE food allergy and to compare it to peer healthy subjects." (PMID 35458127, 2022). "We first examined the gene expressions of IL-4, IL-5, and IL-13 in water-treated mice with or without food allergy." (PMID 36501013, 2022).
food allergy (continued). "OVA-sensitized mice were protected from food allergy anaphylactic death by 60% and observed with significantly suppression of OVA-specific IgE,IL-17, TH2 cytokines (IL-4, IL-5, IL-10, IL-13) and TH1 cytokines (IFN-γ and IL-12) with the treatment of 25 mg/kg of extract." (PMID 31275149, 2019). "In allergic EG patients, but not those with conventional anaphylactic food allergy, a population of IL-5 expressing food allergen specific T cells have been characterized." (PMID 24772356, 2014). "Moreover the presence of a food allergy induced further BAL IL-4 and IL-5 increase in HDM-sensitized mice demonstrating a Th2 response enhancement." (PMID 25433406, 2014). "Although increased production of IgE and Th2 cytokines (IL-4, IL-5 and IL-13) are considered common markers of food allergy, absence of IgE or increased levels of Th1 cytokines (IL-2, IFN-γ and TNF-α) have also been observed in several instances of food allergy, mainly in response to cow's milk." (PMID 21211037, 2011). "Non-IgE-mediated food allergy is believed to be cellular-dependent with a delayed response and a possible mechanism including IL10 and IL5." (PMID 39085570, 2024).
breast carcinoma (37 papers, 2007 to 2025). "Researchers have found that production of the tumorigenic cytokine IL-5 is associated with an enhanced response to immune checkpoint blockade in breast cancer patients." (PMID 38177198, 2024). "Consistent with our MR analysis findings, multiple meta-analyses and observational studies have demonstrated a robust association between the inflammatory cytokines IL-5 and IL-16, and the susceptibility to breast cancer." (PMID 37910571, 2023). "The haplotype AAAACGG in IL5 was associated with a decreased overall breast cancer risk (OR 0.96, 95 % CI 0.93–0.99, p value = 5.0 × 10−3)." (PMID 26621531, 2016). "On the gene level, in addition to TGFBR2 and CCND1, IL5 and GM-CSF showed the strongest associations with overall breast cancer risk (p value = 1.0 × 10−3 and 7.0 × 10−3, respectively)." (PMID 26621531, 2016). "Conversely, increased breast cancer IL-5 expression is associated with metastasis and poor prognosis, while others have found that tumour Th2 cell-derived IL-5 may instead enhance response to immune checkpoint inhibitors in breast cancer." (PMID 37455828, 2023). "Our comprehensive examination of associations between polymorphisms in the immunosuppression pathway genes and breast cancer risk revealed that STAT3, IL5, and GM-CSF may play a role in overall breast cancer susceptibility among women of European ancestry." (PMID 26621531, 2016). "Our data provide evidence that the immunosuppression pathway genes STAT3,IL5, and GM-CSF may be novel susceptibility loci for breast cancer in women of European ancestry." (PMID 26621531, 2016). "Similarly to the case of TNFα, we also found synergistic associations between 25OHD and IL5 on breast cancer ER status in premenopausal patients." (PMID 24473087, 2014). "Our findings demonstrate that the group 2 innate lymphoid cells (ILC2s)‐myeloid‐derived suppressor cells (MDSCs) axis is associated with the unfavorable prognosis of advanced breast cancer in obese patients, and cytokine interleukin‐5 (IL‐5) may be involved in this process." (PMID 38501542, 2024). "In addition, IL5 and GM-CSF may be further potential susceptibility loci of breast cancer (p value = 1.0 × 10−3 and 7.0 × 10−3, respectively)." (PMID 26621531, 2016). "IL-5 and IL-13 have been reported as elevated in some breast cancers, with a potential role for IL-5 in enhancing the response to an immune checkpoint blockade." (PMID 38397942, 2024). "Our findings demonstrate that IL-5, IL-7, and IL-16 are risk factors for HER2-positive breast cancer, with varying degrees of increased probability of HER2-positive breast cancer associated with elevated levels of these inflammatory cytokines." (PMID 37910571, 2023). "The results of the forward MR analysis showed a potential link between IL-5, IL-7, and IL-16 and an increased risk of HER2-positive breast cancer." (PMID 37910571, 2023). "Th2 cell–induced terminal differentiation is driven by IL-3/IL-5/GM-CSF binding to receptors with a common β chain on breast cancer cells, which results in the activation of the signaling transducer and activator of transcription 5 (STAT5) pathway." (PMID 35657353, 2022). "Meanwhile, some studies have reported that IL-5 levels can modify the invasion of cancer or the development of metastasis in breast cancer and bladder cancer." (PMID 32703187, 2020). "Recent reports show that curdlan can inhibit TH2‐cell responses, promoting breast cancer progression 43; it was also reported to suppress IL‐5, IL‐13 and surprisingly IL‐1β from lymph nodes during epicutaneous sensitization." (PMID 26573878, 2016). "When 25OHD and cytokines/ratios were combined in our analyses, synergistic associations on ER status were found between 25OHD and TNFα and IL5, as well as several cytokine ratios, in premenopausal breast cancer patients." (PMID 24473087, 2014).
breast carcinoma (continued). "In this study, we examined the combinational associations of serum levels of 25OHD with plasma levels of three cytokines, IFNα2, TNFα and IL5, as well as ten cytokine ratios, on ER status of breast cancer." (PMID 24473087, 2014). "Importantly, Th2 cell immunity, facilitated by the release of interleukin 3 (IL-3), interleukin 5 (IL-5), and granulocyte-macrophage colony-stimulating factor (GM-CSF), induces terminal differentiation in developing breast cancer." (PMID 39507526, 2024). "Importantly, our study is the first to demonstrate that IL-5, IL-7, and IL-16 play a significant role as risk factors in the development of HER2-positive breast cancer." (PMID 37910571, 2023). "Therefore, it is essential to conduct further follow-up studies to delve deeper into the impact of interleukins (IL-5, IL-7, IL-16, and IL-10) on the two subtypes of breast cancer (HER2-positive and HER2-negative)." (PMID 37910571, 2023). "Moreover, IL-5 was recognized as a crucial mediator of immune checkpoint blockade response in breast cancer." (PMID 37686245, 2023). "In breast cancer, an immune checkpoint blockade increased IL-5 production by CD4+ T cells." (PMID 36980202, 2023). "However, the precise mechanisms by which IL-5, IL-7, and IL-16 contribute to the initiation and metastasis of breast cancer, either via HER2 or other pathways, remain uncertain." (PMID 37910571, 2023). "In contrast, IL-5 and IL-8 have not been found to be significantly associated with breast cancer in this study, and we can further explore his assessment efficacy by expanding the sample size subsequently." (PMID 36531035, 2022). "In contrast, IL-5 and IL-8 have not found to be significantly associated with breast cancer patients in this study, which requires further study." (PMID 36531035, 2022). "In addition, we found positive correlations between TSLP expression and CSF2/IL3/IL5 and differentiation genes expression in human breast cancer." (PMID 35657353, 2022). "Despite the evidence for a possible role of IL5 and GM-CSF in breast cancer susceptibility from the gene-level analysis, no individual SNPs at IL5 or GM-CSF yielded significant genetic associations." (PMID 26621531, 2016). "Despite the lack of statistical significance when considering IL 5 and IL 17 production separately, when we analyzed patients whose CD4+ T-cells produced IL-5 and/or IL-17, we did observe a significant impact on the overall survival (p = 0.01) in these elderly breast cancer patients." (PMID 26500775, 2015). "We show that IL-3, IL-5, and GM-CSF released by Th2 cells are responsible for the induction of terminal differentiation in the developing breast cancer and demonstrate that Th2 cell immunity reverted high-grade breast cancers into low-grade, fibrocystic-like structures." (PMID 35657353, 2022). "However, mutGATA3 failed to activate IL5/GFP expression indicating that the DBD truncation associated with luminal breast cancer diminishes GATA3 activity." (PMID 25410484, 2014). "In contrast, the chronic inflammatory IL signature, including IL-4, IL-5, IL-10, IL-13, IL-17, and CXCL1, showed a significant prognostic effect across the whole cohort of breast cancer patients." (PMID 39456897, 2024). "Using genetically engineered mouse models of breast cancer, Blomberg demonstrated that ICB treatment increased interleukin 5 (IL5) secretion by CD4+ T cells, which in turn increased eosinophil production in the bone marrow." (PMID 37801168, 2023). "For instance, several studies have demonstrated a noteworthy elevation in the concentrations of IL-5, IL-6, IL-7, and TNF-α in both the pathological tissue and systemic circulation of breast cancer patients, as compared to healthy individuals." (PMID 37910571, 2023). "Comparison of serum IL-5, IL-6, IL-8, IL-17 and VEGF levels in the breast cancer surgery group before and after surgery." (PMID 36531035, 2022).
breast carcinoma (continued). "The specific T cell reactivity restores the antitumor immunity in patients with breast cancer, which is affected by release of local cytokine and chemokines like CXC10, CXC9, IFNγ, IL-4 and IL-5." (PMID 33957948, 2021). "Considering the results presented in this study, depletion of Her-2-specific IL-5- and IL-17-producing CD4+ T-cells and enrichment of TNF-producing CD8+ T-cells for adoptive T-cell therapy would be important in breast cancer." (PMID 26500775, 2015). "Our study reveals a genetic correlation between IL-5, IL-7, IL-16, and HER2-positive breast cancer, providing valuable insights for future research on the pathogenesis and pharmacological intervention of HER2-positive breast cancer." (PMID 37910571, 2023). "Serum IL-5, IL-6, IL-8, IL-17, VEGF levels and lymph node metastasis in breast cancer patients." (PMID 36531035, 2022). "Moreover, higher levels of Th2 cytokines—IL-10 and IL-5 —were related to the lack of pathologic complete response after chemotherapy and worse survival in breast cancer patients, respectively." (PMID 31016433, 2019). "In one small study of 105 breast cancer patients, IL5 expression could not be detected in tumor tissues, while in another study of 35 breast cancer patients and 24 women with benign breast diseases, serum IL5 level was significantly higher in cancer patients." (PMID 24473087, 2014). "One of the important observations in our study was the recognition of inflammation related factors in the IPA network and a number of pathway showed IL-5, IL-1β, TNF, IL-4, and INFγ as the central molecules highlighting an already existing relationship between inflammation and breast cancer." (PMID 23216862, 2012). "Furthermore, the specific role of IL-3 and IL-5 versus GM-CSF to breast cancer suppression and the contributions of antigen-nonspecific T cell response and other immune cell types including eosinophils, macrophages, and CD8+ T and NK cells to Th2 cell immunity warrant further investigation." (PMID 35657353, 2022). "Moreover, targeting STAT3 in human breast cancer cells was reported to suppress the tumor progression by regulating the expression of crucial proteins in tumor milieu, such as survivin, chemokines (CCL5 and CXCL10) and proinflammatory cytokines (IL-6, IL-5, TNF-a, and IFN-γ)." (PMID 33957948, 2021). "As previous study has reported that blocking of STAT3 in breast cancer cells induced an antitumor immune response involving CD4+ T cells, which may ameliorate TME via secretion of cytokines, such as TNF-α, IFN-γ, IL-6, and IL-5, as well as chemokines CCL5 and CXCL10." (PMID 33957948, 2021). "On interrogating the serum cytokines in these tumor-bearing mice, we observed a significant upregulation of IL5 and IL27p28 in the ETBF group, similar to the non-tumor-bearing mice, reiterating the protumorigenic role of ETBF in this breast cancer model." (PMID 37503343, 2023). "Limiting the analysis to non-metastatic elderly breast cancer patients only, we still observed a similar negative impact on survival for the patients whose CD4+ T-cells produced IL-5 and/or IL-17 (p = 0.02)." (PMID 26500775, 2015).
eosinophilic diseases (37 papers, 2009 to 2026). "The approval of novel biologic therapies targeting the interleukin-5 pathway can help reduce the use of systemic glucocorticoids (SGC) in eosinophilic diseases and reduce the risk of SGC-related adverse effects (AEs)." (PMID 38250075, 2023). "Additionally, blocking the Pim-1/NFIL3 axis or selective elimination of GR-mediated TA restores apoptosis in IL-5-activated eosinophils suggesting NFIL3’s role in treating eosinophilic disorders associated with steroid resistance." (PMID 37664635, 2023). "Indeed, eosinophilic diseases have been associated with TNFα, IL-5, IL-10, and eotaxin-3, while IL-10 was overexpressed in IgG4RD." (PMID 22333532, 2012). "Drawing on advances in eosinophil subset biology, receptor signaling, and tissue-level immune crosstalk, this review reframes IL-5 biology through the lens of systems-level inflammatory regulation across airway and systemic eosinophilic diseases." (PMID 42123654, 2026). "Following anti-TNF withdrawal, eosinophilic disease persisted, prompting compassionate off-label treatment with benralizumab, an interleukin-5 (IL-5) receptor α-antagonist, alongside vedolizumab for CD maintenance." (PMID 42110122, 2026). "We recommend spatiotemporal exposure assessment (satellite-derived PM2.5/NO2, indoor biomass smoke measures, mold indices), coupled with endotype profiling (IgE, eosinophils, FeNO) to tailor interventions (e.g., anti-IL-5 for eosinophilic disease)." (PMID 41367619, 2025). "Overall, these findings provide an important mechanistic insight into eosinophil priming in eosinophilic disorders and the therapeutic effect of anti-IL-5 treatment." (PMID 38493955, 2024). "Our observations provide new insights into the roles of IL-5 in eosinophilic disorders and biological effect of mepolizumab on eosinophils." (PMID 38493955, 2024). "The US Food and Drug Administration (FDA) has approved several anti-IL-5 therapies targeting eosinophilic disorders." (PMID 39840271, 2024). "There is substantial evidence that IL-5 is a critical cytokine acting on numerous processes in eosinophil biology, driving eosinophilic diseases." (PMID 35720347, 2022). "A role for IL-5 has also been suspected in this eosinophilic disease, as IL-5 is an eosinophil activator that stimulates IgA production, produced by Th2 cells and mast cells." (PMID 35387030, 2021). "Novel therapies targeting IL‐5 signaling are approved for the treatment of eosinophilic asthma, and anti‐IL‐5 and anti‐Siglec‐8 therapies are currently in development for the treatment of diverse eosinophilic diseases." (PMID 29758105, 2018). "Therapeutics targeting type 2 inflammation, including IL-4, IL-5, and IL-13, are currently in development to treat eosinophilic diseases." (PMID 29034234, 2017). "The three β-chain cytokines, IL-3, IL-5, and GM-CSF are all present in human eosinophilic diseases and have both highly redundant and yet critically unique roles in the EOS biology." (PMID 28971096, 2017). "At this time, it is not possible to predicate or predict whether, in the future, CRS patients such as those with eosinophilic disease will all receive anti-IL-5 therapy." (PMID 29707206, 2018). "The role of IL-5 in eosinophilic diseases is reviewed elsewhere in this issue." (PMID 29034234, 2017). "In the disease condition, the excessive cytokines released, such as IL-5 promote the survival and enhance the function of iEOS due to their IL-5-dependent, resulting in high population and hyperactivate of iEOS that may contribute to the pathogenesis of eosinophilic diseases." (PMID 40292285, 2025). "Data presented in our study, including two unreported patients from our medical center, support treatment of DRESS with mAbs directed toward IL-5 or IL-5R, which are already Food and Drug Administration (FDA)-approved for other eosinophilic disorders." (PMID 37187735, 2023).